NPY1R (neuropeptide Y receptor Y1)
Diseases named in the same sentence as NPY1R in open-access papers (continued):
Sharing a sentence is not in itself a finding about the gene and the disease.
Obesity (10 papers, 2013 to 2024). Accumulation of substantial excess body fat. "Similar to previous findings, our study found that GATA3 was a core transcription factor associated with NPY1R expression and was significantly negatively associated with high NPY1R expression in patients with obesity." (PMID 35401881, 2022). "Targeted disruption of the Npy1r gene in limbic areas revealed that limbic NPY-Y1R system was involved in energy balance and emotional behavior, and selective inactivation of limbic Npy1r gene increased susceptibility to diet-induced obesity in male mice." (PMID 36267563, 2022). "In conclusion, here we provided the first demonstration that the inactivation of limbic Npy1r gene increases susceptibility to diet-induced obesity and glucose intolerance in male mice that can be due to a dysregulation of the appetite/satiety balance." (PMID 34445453, 2021). "We suggest that the conditional inactivation of limbic Npy1r gene in Npy1rrfb mice might mimic, at least in part, the mechanisms underlying emotional eating, such as binge eating disorders and associated obesity, a hypothesis that needs further investigations." (PMID 34445453, 2021). "In the current study we examined whether the targeted disruption of Npy1r gene in excitatory neurons of the limbic system of adolescent mice might affect susceptibility to obesity and associated disorders in response to metabolic challenges." (PMID 34445453, 2021). "It has been shown that NPY1R mRNA expression is increased in diet-induced obesity-sensitive rats and decreased in diet-induced resistant rats, suggesting a correlation between Y1R gene expression levels and a genetic predisposition to the development of obesity." (PMID 35401881, 2022). "We used conditional knockout Npy1rrfb and Npy1r2lox control mice to examine whether forebrain disruption of the Npy1r gene affects susceptibility to obesity and associated disorders of cycling and ovariectomized (ovx) female mice in a standard diet (SD) regimen or exposed to an HFD for 3 months." (PMID 35683029, 2022). "In the present study, we used the same conditional system to examine whether the targeted disruption of the Npy1r gene in limbic areas might affect susceptibility to obesity and associated disorders during adulthood in response to a 3-week high-fat diet (HFD) regimen." (PMID 34445453, 2021). "Recently, a study confirmed that peripheral NPY1r antagonism or selective ablation of NPY1r from adipocytes increases thermogenesis and protects from diet-induced obesity." (PMID 36293486, 2022). "Among these, regression analysis found four well-established obesity associated genes that were positively correlated (CPE, LEP, NPY1R, and NPY5R), and two genes (APOM, and CRP) that were negatively correlated with weight gain." (PMID 23544116, 2013). "Having Npy1r downregulated by Pineapple extract suggests its potential role in managing obesity." (PMID 38931172, 2024). "Interestingly, a third group of genes (CPE, NPY5R, DRD3, TAS2R38, SLC18A1, G6PC3, NPY1R, and VLDLR) was highly associated with both neurological and obesity concepts." (PMID 23544116, 2013). "Male mice targeted disruption of the Npy1r gene in limbic areas were used to study the effect of NPY-Y1R system in energy balance and emotional behavior as well as diet-induced obesity." (PMID 36267563, 2022). "In line with previous studies, we found that NPY1R expression was significantly more highly expressed in obese children—the obesity and obesity with fracture groups—than in nonobese children." (PMID 35401881, 2022). "NPY1R expression was significantly upregulated in children with obesity compared to children without obesity (p < 0.05)." (PMID 35401881, 2022).
diabetes (8 papers, 2018 to 2025). "Taken together, our datasets suggest that pancreatic islet architectural benefits of prolonged NPY1R activation in diabetes are partly linked to positive alteration of the transdifferentiation of both alpha- and beta-cells." (PMID 33716983, 2021). "Since diabetes is a metabolic disorder characterized by both aberrant alpha- and beta-cell secretory function, it suggests NPY1R modulation may have extremely credible antidiabetic potential." (PMID 33716983, 2021). "Also, the selective activation of PPARɣ in NPY1R-expressing adipocytes using a molecule that covalently links tesaglitazar to neuropeptide Y was shown to enhance adipocyte differentiation and to prevent diabetes progression in db/db mice." (PMID 35995995, 2022). "NPY and receptors NPY1-R, NPY2-R, and NPY5-R appear to be involved in the pathophysiology of several diseases including diabetes mellitus, heart failure, arterial hypertension and peripheral arterial disease." (PMID 35213955, 2022). "For example, neuropeptide Y receptor Y1 abundance has been found to increase in the rat heart only after 1 year of the duration of diabetes and not 26 or 39 weeks after the induction of diabetes." (PMID 30057556, 2018). "Indeed, our findings in human islets are in line with previous studies revealing that increased islet Npy1r mRNA levels were present in diabetic mice induced by STZ and in aged db/db mice with full-blown diabetes featuring impaired insulin secretion due to dedifferentiated β cells." (PMID 34890851, 2022).
prostate carcinoma (8 papers, 2012 to 2025). A carcinoma that arises from epithelial cells of the prostate gland. "Another study in prostate cancer cells has revealed up-regulation of MCM3AP-AS1 in association with down-regulation of NPY1R." (PMID 35790972, 2022). "In addition, NPY (neuropeptide Y), a member of the NPY family, is widely expressed in the central nervous system, and its receptor, NPY-1R, is associated with the proliferative potential of prostate cancer." (PMID 38732035, 2024). "Previous studies have shown that NPY signaling stimulates cancer cell motility and invasive potential in vitro in breast and prostate cancer cell lines, warranting further investigation of the role of NPY1R in PC cell migration." (PMID 40073121, 2025). "NPY1R is a poor prognostic factor for prostate cancer and melanoma, but its role in pancreatic cancer is not clear." (PMID 33169793, 2020). "Last, immunohistochemical analysis of human patients with prostate cancer found that NPY, NPY1R, NPY2R, and NPY5R expression was all significantly increased at the invasive border relative to the bulk tumor mass." (PMID 40073121, 2025). "Another study in prostate cancer has shown that MCM3AP-AS1 over-expression facilitates cancer development in vivo, which can be inverted by up-regulation of NPY1R." (PMID 35790972, 2022). "Similarly, in prostate cancer (PCa), highly expressed MCM3AP-AS1 facilitates cancer cell progression by recruiting DNMT1/DNMT3 to the NPY1R promoter, which downregulates NPY1R expression and activates the MAPK pathway." (PMID 34461912, 2021).
hepatocellular carcinoma (4 papers, 2017 to 2022). A malignant tumor that arises from hepatocytes. "Via NPY1R, NPY inhibits the growth of hepatocellular carcinomas by inactivating the mitogen-activated protein kinase signaling pathway." (PMID 29100314, 2017). "In non-neuroendocrine related tumors such as in hepatocellular carcinoma cells, npy1r inhibit cell proliferation by activating mitogen-activated protein kinase signal pathway, promoting tumor growth and increasing tumorigenicity of cells." (PMID 35433681, 2022). "The results showed that NPY1R was mainly located in the cytoplasm and there was low expression on the membranes of hepatocytes in control normal livers (CNLs), weak staining in fibrotic livers (LCs) and no staining in hepatocellular carcinoma (HCC) tissues." (PMID 31263154, 2019).
breast tumors (3 papers, 2022 to 2023). "Immunofluorescence analyses of breast tumour and normal tissue was conducted to determine correlation between NPY1R or NPY5R protein levels and a marker of hypoxia (CAIX) in breast carcinoma." (PMID 37264315, 2023). "In human breast tumor tissue, we show via immunofluorescence that NPY5R protein levels and colocalization with hypoxia correlate with advanced cancer, and NPY1R protein correlates with adverse outcomes." (PMID 37264315, 2023). "In summary, we have found NPY1R to be highly expressed and hyperphosphorylated GPCR in LumA breast tumors of patients." (PMID 35121782, 2022). "Among the shared upregulated genes in normal breast tissues and breast tumors, the expression of five genes unique to young women aged ≤40 years with BC (i.e., COL1A2, COL5A2, COL5A1, NPY1R, and KIAA1644) significantly affected the OS and RFS of patients with several tumor subtypes." (PMID 35741056, 2022).
lymph node metastasis (3 papers, 2015 to 2025). "These high levels of NPY1R expression were positively correlated with the clinical stage and lymph node metastasis status of the disease, as well as with the status of the estrogen and progesterone receptors (P<0.05)." (PMID 25624911, 2015).
melanoma (3 papers, 2020 to 2022). A malignant, usually aggressive tumor composed of atypical, neoplastic melanocytes. "Additionally, our study identified genes without reported expression in CMM and nevi or biological function related to melanoma progression, including CCL3L3, NPY1R, IL11A, FCGR1B, OAS2, ASB11, FCGR3A, and GLA." (PMID 35008167, 2021). "Among them, only PDZD2, NPY1R and ADH1B have not been reported in melanoma studies, and EMP3 has only been reported in uveal melanoma." (PMID 35433681, 2022).
pancreatic cancer (3 papers, 2005 to 2025). "Transcriptomic and proteomic assessment via RNA-seq and MS, respectively, identified ~500 differentially expressed transcripts and proteins in pancreatic tumors following Npy1r knockout." (PMID 40073121, 2025). "We therefore assessed the pancreatic tumor microenvironment in end-stage tumors of the whole-body Npy1r knockout using IHC." (PMID 40073121, 2025). "Finally, previous expression profile studies have found NPY1R to be substantially induced in many breast, prostate and pancreatic carcinomas." (PMID 15836779, 2005).
Alzheimer disease (2 papers, 2024). A progressive, neurodegenerative disease characterized by loss of function and death of nerve cells in several areas of the brain leading to loss of cognitive function such as memory and language. "Additionally, studies have shown a decrease in NPY-immunoreactive fibers within the dentate gyrus in Alzheimer’s disease models, indicating the potential of NPY1R agonists in modulating hippocampal functions." (PMID 38667284, 2024). "While the singular administration of an NPY1R agonist or Ketamine did not produce significant results in our object-in-place task, the literature suggests that NPY and its agonists have the capacity to ameliorate spatial memory deficits in rodent models mimicking Alzheimer’s disease symptoms." (PMID 38667284, 2024).
asthma (2 papers, 2024 to 2025). "To comprehensively understand the impact of NPY1R expression on sensory neurons on the asthma phenotype, we generated mice with a conditional knockout of this receptor in nociceptors (NaV1.8cre::Npy1rfl/fl)." (PMID 39345572, 2024). "Our single cell RNA sequencing data now reveal that NPY1R-expressing nociceptor amplify, the regulation and function of T cells, with implications for asthma, allergies, and broader inflammatory processes." (PMID 39345572, 2024). "Future work will reveal whether targeting vagal NPY1R constitutes a relevant therapeutic target to quell asthma-induced bronchoconstriction and cough." (PMID 39345572, 2024). "This supports the hypothesis that NPY1R reduces airway nociceptor activity, thereby diminishing their impact on the airway immune response in asthma." (PMID 39345572, 2024).
gastric tumor (2 papers, 2018 to 2024). "Specifically in GC, NPY1R is more highly expressed in the subgroup of gastric tumors presenting MUC16 mutations, and, in agreement with our results, the high expression of NPY1R was associated with dismal prognosis in the GC patients from the TCGA and ACRG cohorts." (PMID 38480611, 2024). "Among these genes, we further selected six GI hormone receptors whose expression was significantly down-regulated by 80–100% in the primary gastric tumors, including neuropeptide Y receptors (NPY1R and PPYR1), prostanoid receptors (PTGDR, PTGER2, and PTGER3), and a somatostatin receptor (SSTR2)." (PMID 30510283, 2018). "The qRT-PCR and bisulfite sequencing analyses of the six genes (NPY1R, PPYR1, PTGDR, PTGER2, PTGER3, and SSTR2) demonstrated a negative correlation between methylation and gene expression in two sets of paired gastric tumor and normal tissues." (PMID 30510283, 2018).
type 2 diabetes (2 papers, 2022 to 2024). "•Increased islet NPY and NPY1R levels are observed in human type 2 diabetes." (PMID 34890851, 2022).
allergies (1 paper, 2024). "To identify these neuromodulators, we exposed (24h) cultured JNC neurons to various allergy driving cytokines, inflammatory lipids, and neurotrophins, and used transcription changes to Npy1r, Sting1, Bdnf, and Il6 as proxies for an AAI-like signature." (PMID 39345572, 2024).
autism (1 paper, 2021). Persistent deficits in social interaction and communication and interaction as well as a markedly restricted repertoire of activity and interest as well as repetitive patterns of behavior. "NPY1R expression has been associated with anxious temperament in monkeys and deletion involving NPY1R has been identified in a case study of autism." (PMID 34798907, 2021).
autoimmune thyroiditis (1 paper, 2021). "The expression of NTSR1 was significantly lower compared to the increased expression of NPY1R in patients with hypothyroidism caused by autoimmune thyroiditis." (PMID 34104248, 2021). "The patients with hypothyroidism caused by autoimmune thyroiditis had considerably lower expression of NTSR1, while the expression of NPY1R increased." (PMID 34104248, 2021).
cardiac hypertrophy (1 paper, 2021). "To functionally analyze whether NPY1R/miR-216b/FoxO4 signal pathway is a necessary condition for NPY-induced cardiac hypertrophy, we transfected NPY into myocardial cells alone or in combination with BIBO3304 or miR-216b mimic or FoxO4 siRNA." (PMID 33390770, 2021). "NPY1R/miR-216b/FoxO4 pathway is critical for NPY induced cardiac hypertrophy." (PMID 33390770, 2021).
colitis (1 paper, 2015). Inflammation of the colon. "Mice with colitis showed altered stress-associated behaviour, which is associated with colitis-induced alterations of Npy, Npy1r, Crh, Crhr1, Bdnf and Nr3c1 gene expression in distinct regions of the brain." (PMID 26066467, 2015). "In the hippocampus, colitis did not alter Npy expression, but increased Npy1r and decreased Crhr1 mRNA levels." (PMID 26066467, 2015).
colorectal cancer (1 paper, 2022). A primary or metastatic malignant neoplasm that affects the colon or rectum. "Two of the last-mentioned hub genes (P2RY14, and NPY1R), to the best of our knowledge, have not already been reported as being under-expressed in colorectal cancer." (PMID 35333898, 2022).
epilepsy (1 paper, 2024). A brain disorder characterized by episodes of abnormally increased neuronal discharge resulting in transient episodes of sensory or motor neurological dysfunction, or psychic dysfunction. "Based on the literature and database searches, there is association with seizures or epilepsy for five of the brain expressed genes (Marchf1, Tma16, Npy1r, Npy5r, Psd3)." (PMID 38862622, 2024).
glioblastoma (1 paper, 2025). The most malignant astrocytic tumor (WHO grade IV). "The neuropeptide-related genes, including PPY and members of the NPY family (e.g., NPY, NPY1R, NPY2R, NPY4R, NPY5R, PYY), form a distinct cluster characterized by strong co-expression and shared pathway interactions, indicating a potential role in neuroendocrine signaling relevant to glioblastoma." (PMID 40725410, 2025).
hepatitis B (1 paper, 2021). "Also, the upregulation of them (except for NPY1R) indicated better outcomes of HCC patients with a history of hepatitis B, though hepatitis B virus infection is an independent risk factor of HCC vascular invasion." (PMID 33878734, 2021).
Hyperinsulinemia (1 paper, 2015). An increased concentration of insulin in the blood. "In mice, a triple knockout of NPY1R, NPY2R and NPY4R prevents the hyperinsulinemia associated with NPY overexpression, indicating that NPY signalling through the NPY receptors modulates insulin secretion." (PMID 26138755, 2015).
hypopharyngeal cancers (1 paper, 2018). Carcinoma, predominantly squamous cell, arising from the epithelial cells of the hypopharynx. "Notably, the less frequently methylated genes (less than 30%) were as follows: CDH13, p16, MGMT, GAL, NPY, GALR2, and VEGFR3 for hypopharyngeal cancers; CDH13, p16, RASSF1A, GAL, NPY, and NPY1R for laryngeal cancers; and CDH13 and GAL for oral cavity cancers." (PMID 29361757, 2018).
hypothyroidism (1 paper, 2021). Abnormally low levels of thyroid hormone. "Our research found that patients with postoperative hypothyroidism had a considerably increased expression of NPY1R, NTSR1, and NPY4R." (PMID 34104248, 2021). "Our research identified that patients with postoperative hypothyroidism had a considerably increased expression of NPY1R, NTSR1, and NPY4R." (PMID 34104248, 2021). "The results from the RT2 Profiler Neuropeptides and receptor pathway-focused gene expression analysis indicated that in Group 1, which includes patients with postoperative hypothyroidism, among anti-apoptotic genes, the expression of NPY1R and NTSR1 was increased by 3.0 and 3.7 times, respectively." (PMID 34104248, 2021). "In patients with hypothyroidism as a result of AIT (Group 2), the expression of NPY1R was upregulated (5.5-fold)." (PMID 34104248, 2021). "We found that in patients with hypothyroidism related to AIT and postoperative hypothyroidism, NPY1R expression increased." (PMID 34104248, 2021).
Infertility (1 paper, 2026). "Targeting NPY1R is expected to be a potential therapeutic strategy for improving ovarian function and infertility in advanced-age women." (PMID 42262763, 2026).
metastatic cancer (1 paper, 2023). A carcinoma which has spread from the original site of growth to another anatomic site. "Further, there was a higher overall protein expression of NPY5R (2.30-fold) and CAIX (2.12-fold), but not NPY1R, in metastatic cancer relative to non-metastatic cancer." (PMID 37264315, 2023).
myeloma (1 paper, 2016). "Here, NPY1R was significantly down-regulated in osteocytes co-cultured with myeloma cells, inhibiting bone remodeling." (PMID 27405725, 2016). "In conclusion, a total of 393 DEGs were identified between osteocytes co-cultured with and without myeloma cells, and KLF4, IRF8, EGF, EGR1, S1PR1, C3AR1, and NPY1R might be involved in osteocyte cell apoptosis induced by MM cells." (PMID 27405725, 2016).
myocardial ischemia (1 paper, 2019). A disorder of cardiac function caused by insufficient blood flow to the muscle tissue of the heart. "NPY significantly increases infarct area in relation to the area at risk during myocardial ischemia–reperfusion (I/R) injury, which is blunted by NPY1R antagonist BIBO3304." (PMID 31708788, 2019).
neuropathic pain (1 paper, 2023). Chronic pain caused by damage to nerve fibers. "Among these, Npy1r-expressing interneurons (Y1-INs) represent a particularly promising, druggable, pharmacotherapeutic target for the treatment of neuropathic pain." (PMID 37824208, 2023). "We conclude that Grp/Npy1r-INs are conserved in higher order mammalian species and represent a promising and precise pharmacotherapeutic target for the treatment of neuropathic pain." (PMID 37824208, 2023).